ARGFX (arginine-fifty homeobox)
Description:
Transcription factor that acts as activator.
Tractability: No criterion of Open Targets' tractability assessment is met for any kind of drug.
Gene: Protein-coding gene on chromosome 3 (121,567,949 to 121,590,622, forward strand). Ensembl gene ENSG00000186103.
Subcellular location: Nucleus
Gene Ontology:
Molecular function: sequence-specific double-stranded DNA binding; DNA-binding transcription factor activity, RNA polymerase II-specific; RNA polymerase II cis-regulatory region sequence-specific DNA binding; DNA binding
Biological process: regulation of transcription by RNA polymerase II; regulation of DNA-templated transcription
Cellular component: chromatin; nucleus
Genetic constraint (gnomAD): Loss-of-function variants: 9 observed, 7.55 expected, observed/expected ratio (o/e) 1.19, 90% interval 0.71 to 1.84. That is too few expected variants to judge how well the gene tolerates losing a copy. Missense variants: 271 observed, 329.96 expected, observed/expected ratio (o/e) 0.82, 90% interval 0.74 to 0.91. Synonymous variants: 115 observed, 120.88 expected, observed/expected ratio (o/e) 0.95, 90% interval 0.82 to 1.11.
Homologues: Orthologues: chimpanzee ARGFX (97% identical). Paralogues in human: PAX3 (23% identical), OTX2 (23% identical), PAX7 (23% identical), CRX (21% identical), OTX1 (21% identical), ALX4 (19% identical), ARX (19% identical), UNCX (18% identical), EVX1 (18% identical), OTP (18% identical), PITX2 (18% identical), RAX (18% identical), and 38 more.
Diseases named in the same sentence as ARGFX in open-access papers:
ARGFX is named in the same sentence as 2 diseases in open-access papers, as found by Europe PMC text mining. Sharing a sentence is not in itself a finding about the gene and the disease. The quoted sentences say what the papers report.
Stroke (1 paper, 2020). Sudden impairment of blood flow to a part of the brain due to occlusion or rupture of an artery to the brain. "A non‐synonymous variant in the arginine‐fifty homeobox gene (ARGFX) was previously associated with stroke in SCD." (PMID 32898326, 2020).
testis tumor (1 paper, 2010). "The existence of two human retrotransposed pseudogenes derived from ARGFX, three ESTs from human testis tumor and a weakly positive RT-PCR amplification from human testis and embryonic stem cells indicates a low level of ARGFX transcription in humans." (PMID 20565723, 2010).